MAN2B1 (mannosidase alpha class 2B member 1)
Description:
Can hydrolyze a variety of glycan substrates containing terminal alpha-mannosidic linkages. Cleaves alpha 1,2-, alpha 1,3-, and alpha 1,6-linked mannose residues on oligosaccharides generated by N-glycoprotein degradation pathways.
Synonyms: Laman; MANB
Tractability: Small molecule: a high-quality ligand is known; it belongs to a druggable protein family. Antibody: its Gene Ontology location is reachable by antibodies, with high confidence; UniProt predicts a signal peptide or a membrane-spanning region. PROTAC: ubiquitination databases record sites on it; its protein half-life has been measured; a small molecule that binds it is known.
Target class: Enzyme; Hydrolase
Gene: Protein-coding gene on chromosome 19 (12,643,831 to 12,666,762, reverse strand). Ensembl gene ENSG00000104774.
Subcellular location: Lysosome lumen; Secreted
Subcellular location (Human Protein Atlas): Nucleoplasm; Vesicles
Pathways (Reactome):
Immune System: Neutrophil degranulation
Metabolism: Lysosomal oligosaccharide catabolism
Gene Ontology:
Molecular function: alpha-mannosidase activity; carbohydrate binding
Biological process: glycoprotein catabolic process; carbohydrate metabolic process; mannose metabolic process
Cellular component: extracellular exosome; extracellular region; lysosomal lumen; azurophil granule lumen; lysosome
Genetic constraint (gnomAD): Loss-of-function variants: 93 observed, 123.03 expected, observed/expected ratio (o/e) 0.76, 90% interval 0.64 to 0.9. The upper end of that interval is the gene's LOEUF score, 0.9, which puts it in group 3 of 6, group 1 being the genes least tolerant of losing a copy. Missense variants: 1,293 observed, 1,384.7 expected, observed/expected ratio (o/e) 0.93, 90% interval 0.89 to 0.98. Synonymous variants: 569 observed, 568.06 expected, observed/expected ratio (o/e) 1, 90% interval 0.93 to 1.07.
Gene-disease validity (ClinGen):
ClinGen rates the evidence that MAN2B1 causes each of these diseases.
alpha-mannosidosis (autosomal recessive): Definitive. Alpha-mannosidosis is an inherited lysosomal storage disorder characterized by immune deficiency, facial and skeletal abnormalities, hearing impairment, and intellectual deficit.
Homologues: Orthologues: chimpanzee MAN2B1 (99% identical), macaque WDR83OS (97% identical), guinea pig MAN2B1 (77% identical), pig MAN2B1 (76% identical), mouse Man2b1 (76% identical), dog MAN2B1 (75% identical), rat Man2b1 (75% identical), tropical clawed frog man2b1 (58% identical), zebrafish man2b1 (56% identical), Drosophila melanogaster LManII (45% identical), Drosophila melanogaster LManI (40% identical), Drosophila melanogaster LManIV (39% identical), and 4 more. Paralogues in human: MAN2B2 (27% identical), MAN2A2 (27% identical), MAN2A1 (27% identical), MAN2C1 (16% identical).
Diseases named in the same sentence as MAN2B1 in open-access papers:
MAN2B1 is named in the same sentence as 50 diseases in open-access papers, as found by Europe PMC text mining. Sharing a sentence is not in itself a finding about the gene and the disease. The quoted sentences say what the papers report.
alpha-mannosidosis (20 papers, 2008 to 2026). "Alpha-mannosidosis is a rare lysosomal storage disorder caused by MAN2B1 mutations, leading to cognitive decline, hearing loss, infections, and skeletal abnormalities." (PMID 41567994, 2026). "This study provides the first molecular insight into alpha-mannosidosis among Iraqi children, revealing both known and novel variants in the MAN2B1." (PMID 41567994, 2026). "Early genomic investigation (eg, genome, exome, lysosomal storage disorder genes, or MAN2B1 sequencing) and biochemical diagnostics are recommended for patients with learning disability and hearing impairment to reduce diagnostic delays for alpha-mannosidosis." (PMID 41334501, 2025). "The index patient was a seven-year-old girl who was referred with a confirmed diagnosis of alpha-mannosidosis based on the presence of homozygous c.437-1G>A mutation in the MAN2B1 gene." (PMID 38800253, 2024). "While reported cases of alpha-mannosidosis resulting from structural mutations in the MAN2B1 gene are limited, this is likely to have had a minimal impact on the underestimation of carrier frequency." (PMID 38107468, 2023). "Alpha-mannosidosis is an autosomal recessive lysosomal storage disorder (OMIM #248500) caused by mutations in the MAN2B1 gene, resulting in reduced activity of the alpha-mannosidase enzyme." (PMID 38107468, 2023). "Alpha‐mannosidosis (AM), an autosomal recessive disorder caused by pathogenic biallelic variants in the MAN2B1 gene, leads to lysosomal alpha‐mannosidase deficiency and accumulation of mannose‐rich oligosaccharides." (PMID 36873087, 2023). "Among other mannosidases, human MAN1B1 deficiency has been linked to intellectual disability and MAN2B1 deficiency in humans causes a lysosomal storage disease known as alpha-mannosidosis." (PMID 35967980, 2022). "Alpha-Mannosidosis (AM) is an ultra-rare storage disorder caused by a deficiency of lysosomal alpha-mannosidase encoded by the MAN2B1 gene." (PMID 34614013, 2021). "Alpha-mannosidosis (OMIOM 248500) is a rare autosomal recessive lysosomal storage disorder caused by pathogenic variants in the MAN2B1 gene, resulting in a deficiency of lysosomal alpha-mannosidase activity (EC3.2.1.24)." (PMID 32292699, 2020). "MAN2B1 codes for lysosomal α-mannosidase (LAMAN = MAN2B1, EC 3.2.1.24), the enzyme deficient in alpha-mannosidosis (MIM# 248500)." (PMID 32883051, 2020). "The MAN2B1 cloning and its structure have allowed for the identification and characterization of many mutations causing alpha-mannosidosis." (PMID 29772816, 2018). "Alpha-mannosidosis is caused by mutations in MAN2B1, leading to loss of lysosomal alpha-mannosidase activity." (PMID 26048034, 2015). "Alpha-mannosidosis is caused by pathogenic sequence variants in MAN2B1, leading to loss of lysosomal alpha-mannosidase activity." (PMID 26048034, 2015). "Alpha-mannosidosis (OMIM 248500) is a rare lysosomal storage disorder caused by the deficiency of alpha-Mannosidase (MAN2B1, EC 3.2.1.24), a lysosomal enzyme responsible for the degradation of N-linked oligosaccharides." (PMID 23786919, 2013). "In alpha-Mannosidosis broad heterogeneity is seen not only in the clinical manifestations, but also in the spectrum of mutations of the alpha-Mannosidase gene (MAN2B1) that is located on chromosome 19p13.2." (PMID 23786919, 2013). "Alpha-mannosidosis is caused by mutations in the MAN2B1 (LAMAN) gene encoding lysosomal α-mannosidase." (PMID 18651971, 2008). "Alpha-mannosidosis is inherited in an autosomal recessive fashion and is caused by mutations in the MAN2B1 gene located on chromosome 19 (19 p13.2-q12)." (PMID 18651971, 2008). "A rare but devastating human Lysosomal Storage Disease known as Alpha Mannosidosis is caused by mutations in the human gene MAN2B1, which is related to all of the lysosomal alpha-mannosidases knocked down by RNAi against sens-2 in our experiments, with LManII being the closest ortholog." (PMID 36652461, 2023).
alpha-mannosidosis (continued). "Alpha‐mannosidosis (AM; OMIM 248500) is a rare autosomal recessive lysosomal storage disorder caused by mutations in MAN2B1, which codes for the lysosomal alpha‐mannosidase enzyme (LAMAN; EC:3.2.1.24)." (PMID 39926434, 2025). "Alpha-mannosidosis (OMIM 248500) is caused by the deficient activity of a lysosomal hydrolase, alpha-mannosidase (MAN2B1, EC 3.2.1.24), which is responsible for the degradation of N-linked oligosaccharides." (PMID 33669444, 2021). "MAN2B1, a member of the alpha-mannosidase family, was reported to be closely related to alpha-mannosidosis." (PMID 34544412, 2021). "For alpha-mannosidosis, the inclusion of MAN2B1 in genomic panels could significantly reduce and improve diagnostic accuracy because molecular findings are generally more reliable than biochemical markers for this condition." (PMID 41334501, 2025). "Firstly, this study did not assess structural variations, such as large deletions or insertions in the MAN2B1 gene, which may have led to an underestimation of the carrier frequency of alpha-mannosidosis." (PMID 38107468, 2023). "A clinical spectrum of symptoms and disease progression is seen with alpha-mannosidosis, ranging from mild to severe, with severity impacted in part by level of residual alpha-mannosidase activity and subcellular localization of mutant MAN2B1 protein." (PMID 32292699, 2020). "We performed a proband-only exome and detected two homozygous mutations in two different genes: MAN2B1 (Mannosidase Alpha Class 2B Member 1) and SLC7A7 (Solute Carrier Family 7 Member 7), in which mutations cause alpha-mannosidosis and lysinuric protein intolerance respectively." (PMID 31362757, 2019). "Factors such as access to genetic testing and inclusion of MAN2B1 in genetic panels may also contribute to diagnostic delays; in the case of patient NA06, several genetic disorders were screened before finding a specialist who tested for alpha-mannosidosis." (PMID 41334501, 2025). "The A and B forms are the product of a single gene (MAN2B1), as demonstrated in the lysosomal storage disease alpha-mannosidosis (MIM 248500) in which both A and B are lacking." (PMID 29772816, 2018).
lysosomal storage disease (7 papers, 2022 to 2026). A metabolic disorder caused by mutations in proteins critical for lysosomal function, including lysosomal enzymes, lysosomal integral membrane proteins, and proteins involved in the post-translational modification and trafficking of lysosomal proteins. "Dysfunction of MAN2B1 has been implicated as causative factors in mannosidosis, a lysosomal storage disorder characterised by cognitive impairment, hearing loss and immune system and skeletal anomalies." (PMID 39628046, 2024). "Deficiency in MAN2B1 leads to impaired lysosomal function and compromised glycoprotein degradation, resulting in the gradual accumulation of mannose-rich oligosaccharides in cells and tissues, culminating in α-lysosomal storage disease." (PMID 39628046, 2024). "Variants in MAN2B1 causes autosomal recessive α-mannosidosis, a lysosomal storage disease." (PMID 39280098, 2024).
Intellectual disability (5 papers, 2014 to 2024). "Interestingly, the loss of function of three of the six human-biased glycan degradation genes (MANBA, MAN2B2, and MAN2B1) is associated with intellectual disability." (PMID 36658652, 2023).
glioma (4 papers, 2022 to 2024). A benign or malignant brain and spinal cord tumor that arises from glial cells (astrocytes, oligodendrocytes, ependymal cells). "Based on GO and KEGG enrichment analysis findings, the abnormal expression of MAN2B1 is associated with immune system alterations in glioma." (PMID 35186771, 2022). "Our study revealed that MAN2B1 is a potential prognostic biomarker in glioma and associates with immune infiltrates." (PMID 35186771, 2022). "Different frequencies of somatic mutations were found in gliomas between high and low MAN2B1 expression." (PMID 35186771, 2022). "In this study, RNA-seq data from The Cancer Genome Atlas and the Chinese Glioma Genome Atlas datasets were analyzed to explore the correlation between MAN2B1 and clinicopathological features, prognosis, and somatic mutations in gliomas." (PMID 35186771, 2022). "Collectively, we believe that MAN2B1 influences the prognosis of glioma through immune response and cancer-related hallmark signaling pathways." (PMID 35186771, 2022). "In this study, RNA-seq data from TCGA and CGGA datasets were analyzed to explore the correlation of the expression of MAN2B1 and clinicopathological features, prognosis, and somatic mutations in gliomas." (PMID 35186771, 2022). "Taken together, MAN2B1 is a potential prognostic biomarker in glioma and associates with immune infiltration." (PMID 35186771, 2022). "The TCGA and CGGA data showed that MAN2B1 expression was significantly upregulated in glioma tissues and was associated with WHO grade, IDH1 mutation status, and histological subgroups of glioma patients." (PMID 35186771, 2022). "As IDH mutation status is the dominant molecular marker for glioma patients, we analyzed MAN2B1 expression level against IDH mutation status in both pooled and separated WHO grades." (PMID 35186771, 2022). "Additionally, frequencies of somatic mutations present in gliomas with elevated and inhibited MAN2B1 expression differed significantly." (PMID 39404425, 2024). "Specifically, the overexpression of MAN2B1 in glioma tissues is associated with immune response and anti-inflammatory functions by correlating with the expression of tumor-associated macrophages and M2 macrophages, and correlates with malignant clinical features and poor outcome for glioma patients." (PMID 37601653, 2023). "As macrophage polarization contributes to glioma tumorigenesis and MAN2B1 is positively correlated with immune response pathways and immune cells infiltration, we examined whether MAN2B1 is associated with the macrophage polarization." (PMID 35186771, 2022). "Two recent RNA sequencing-based bioinformatic analytical studies have identified MAN2B1 as a novel prognostic biomarker for glioma, indicating that higher expression of MAN2B1 correlates with shorter survival times among patients." (PMID 39628046, 2024). "Their results based on the RNA-seq data indicated that MAN2B1 expression was elevated in glioma and was correlated with malignant clinical and molecular features." (PMID 39404425, 2024). "MAN2B1 in bladder urothelial carcinoma, breast invasive carcinoma, colon adenocarcinoma, glioblastoma multiforme, low-grade gliomas, and laryngeal cancer." (PMID 37601653, 2023). "We found that MAN2B1 was elevated in glioma and was correlated with malignant clinical and molecular features." (PMID 35186771, 2022). "Overall, these results confirmed that MAN2B1 expression was upregulated in glioma tissues, and its expression was correlated with glioma WHO grade." (PMID 35186771, 2022). "To further validate the elevated expression of MAN2B1 in glioma, we tested a series of glioma patient samples from Xiangya Hospital." (PMID 35186771, 2022). "The heatmap showed that enriched pathways and MAN2B1 expression shared the same trend, thus suggesting that immune-related activation is involved in the glioma progression and influenced the prognosis of glioma patients." (PMID 35186771, 2022).
glioma (continued). "First of all, we evaluated the mRNA expression of MAN2B1 in 8 pairs of glioma tissue samples (4 GBM and 4 LGG) and adjacent normal brain tissues by RT-qPCR." (PMID 35186771, 2022). "To investigate MAN2B1 expression in glioma, we analyzed the RNA-seq data in TCGA and CCGA databases." (PMID 35186771, 2022). "We further employed the CIBERSORT algorithm to identify the correlations between the total of 22 TIICs with MAN2B1 expression in gliomas." (PMID 35186771, 2022). "Meanwhile, upregulated expression of MAN2B1 in glioma was validated by RT-qPCR, WB, and IHC staining using clinical glioma samples and glioma cell lines (SHG44, T98G, U251, LN229, U87, and A172)." (PMID 35186771, 2022). "Given that MAN2B1 is considered as an independent prognostic factor for glioma patients, we conducted GO and KEGG enrichment analysis on TCGA and CGGA database to explore the molecular function of MAN2B1 in gliomas." (PMID 35186771, 2022). "Overall, our findings indicated that MAN2B1 was an adverse and independent prognostic factor in patients with glioma." (PMID 35186771, 2022). "Our data suggested that elevated expression of MAN2B1 was correlated with clinicopathological features and can be used as a poor predictive factor in glioma patients." (PMID 35186771, 2022). "Upregulated expression of MAN2B1 is prognostic for poor outcomes in glioma patients." (PMID 35186771, 2022). "In this study, RNA-seq data from The Cancer Genome Atlas (TCGA) and the Chinese Glioma Genome Atlas (CGGA) datasets were analyzed to explore the correlation between MAN2B1 expression and clinicopathological features, prognosis, and somatic mutations in gliomas." (PMID 35186771, 2022). "As a result, we believe that MAN2B1 participates in immune response activation of glioma." (PMID 35186771, 2022). "Higher MAN2B1 mRNA expression was found in glioma tissue than in adjacent normal brain tissues." (PMID 35186771, 2022). "Altogether, these results indicated that high MAN2B1 may promote macrophage polarization, thus contributing to glioma tumorigenesis." (PMID 35186771, 2022). "In order to validate whether MAN2B1 expression may influence the macrophage subtypes in glioma, we analyzed the correlation between MAN2B1 and TAMs biomarker genes." (PMID 35186771, 2022). "We found that MAN2B1 was over-expressed in wild-type IDH gliomas." (PMID 35186771, 2022). "In this study, we found that MAN2B1 expression was positively correlated with the proportion of M2 macrophages, whereas M1 macrophages showed a weaker correlation, suggesting that MAN2B1 was involved in regulating the proportion of TIICs in glioma." (PMID 35186771, 2022). "Furthermore, following strata analysis, we found that the adverse prognostic value of MAN2B1 was independent to WHO glioma grades." (PMID 35186771, 2022). "Hence, our results suggest that MAN2B1 is a prognostic factor closely correlated with glioma patients’ outcomes." (PMID 35186771, 2022). "Since the MAN2B1 expression was positively correlated with the WHO grade, we tested whether MAN2B1 is a prognostic marker for glioma patients." (PMID 35186771, 2022). "Next, we tested MAN2B1 expression in glioma and normal astrocyte cell lines." (PMID 35186771, 2022). "However, the relationship between MAN2B1 and glioma malignancy needs to be further understood." (PMID 35186771, 2022). "However, so far, the relationship between MAN2B1 protein and glioma remains poorly understood." (PMID 35186771, 2022). "Compared with normal astrocyte HEB cell lines, overexpression of MAN2B1 was found in T98G, U251, LN229, U87, and A172 glioma cells." (PMID 35186771, 2022). "We found that the MAN2B1 expression was an independent prognostic factor for OS and PFS in patients with glioma (high vs. low, HR= 1.33, 95%CI= 1.03-1.70, p =0.028)." (PMID 35186771, 2022). "However, the relationship between MAN2B1 and glioma malignancy remains unclear." (PMID 35186771, 2022).
glioma (continued). "However, there is a lack of evidence on the relationship between MAN2B1 and immune infiltration in gliomas." (PMID 35186771, 2022).
colon adenocarcinoma (3 papers, 2022 to 2024). "Elevated expression of MAN2B1 has been found in several cancers, including bladder urothelial carcinoma, breast invasive carcinoma, colon adenocarcinoma, glioblastoma multiforme, low-grade gliomas, and laryngeal cancer." (PMID 37601653, 2023). "Elevated MAN2B1 was found in the majority of human cancers, such as bladder urothelial carcinoma (BLCA), breast invasive carcinoma (BRCA), colon adenocarcinoma (COAD)." (PMID 35186771, 2022). "Analysis of The Cancer Genome Atlas (TCGA) data unveiled elevated mRNA levels of MAN2B1 across numerous human cancers, encompassing bladder urothelial carcinoma (BLCA), breast invasive carcinoma (BRCA) and colon adenocarcinoma (COAD)." (PMID 39628046, 2024).
cognitive decline (2 papers, 2021 to 2026). "We hypothesize that GHR and SLC19A3 genes might act either as genetic modifiers that exacerbate the severity of cognitive decline induced by the primary disease-causing mutation in the MAN2B1 gene or as additional disease loci co-segregating with AM." (PMID 34614013, 2021).
Cognitive impairment (2 papers, 2021 to 2024). Abnormal cognition is characterized by deficits in thinking, reasoning, or remembering. "This is illustrated by the faster disease progression observed in patient TNDF182-6, who manifested an earlier onset of cognitive impairment, although she is carrying the same MAN2B1 gene mutation." (PMID 34614013, 2021).